TAGLN2 (transgelin 2)
Diseases named in the same sentence as TAGLN2 in open-access papers (continued):
Sharing a sentence is not in itself a finding about the gene and the disease.
tumor (continued). "Remarkably, about 48% of tumor tissues showed positive TAGLN2 staining in the nucleus (22.5% of which had a score ≥1), a figure substantially higher than that of adjacent normal tissues (9.3%)." (PMID 39168971, 2024). "Cisplatin or MK2206 treatment showed retarded tumor growth; moreover, combination therapy of the two showed a stronger inhibitory effect both in NC and TAGLN2-overexpressing group." (PMID 39168971, 2024). "In several other neoplasms, TAGLN2 promoter hypermethylation is also observed in patients with a good prognosis." (PMID 39123378, 2024). "The tumor cell lines expression levels from the CCLE confirmed the TAGLN2 mRNA expression discrepancy." (PMID 37476180, 2023). "Secondly, we suggest a strong correlation between TAGLN2 expression and the composition and specific function of the tumor microenvironment, which is preponderant in regulating tumor progression and modulating response to standard-of-care therapies." (PMID 37476180, 2023). "Here, we present experimental evidence indicating that ER stress responses cripple anti-tumor T cell function by disabling TAGLN2-coordinated immunometabolic programs." (PMID 38168227, 2023). "Accordingly, chimeric antigen receptor T cells overexpressing TAGLN2 bypassed the detrimental effects of tumor-induced ER stress and demonstrated superior therapeutic efficacy in mice with metastatic ovarian cancer." (PMID 38168227, 2023). "These discoveries augmented the understanding of the functions of TAGLN2 in tumor growth and advancement, providing inspiration for clinical applications of TAGLN2-targeted therapies down the line." (PMID 37476180, 2023). "Taken together, the outcomes of these studies showed that TAGLN2 was deeply involved in tumor immunity." (PMID 37476180, 2023). "All in all, consistent with previous studies, in UCEC, TAGLN2 was upregulated in cell lines and tumor tissues and led to a pro-tumorigenic effect." (PMID 37476180, 2023). "Through the publically online database cBioPortal, we curated a pan-cancer analysis of TAGLN2 genetic alteration in various tumor samples from TCGA datasets." (PMID 37476180, 2023). "Overall, these results hinted that the expression level of TAGLN2 had an impact on the sensitivity of anti-tumor drugs." (PMID 37476180, 2023). "TAGLN2 is abnormally expressed in a variety of cancers 18, and its deregulation is considered to correlate with tumorigenesis and tumor development." (PMID 34093830, 2021). "Strikingly, non-viral transduction of cell-permeable, de-ubiquitinated recombinant transgelin-2 potentiated DC functions to suppress tumor growth and metastasis." (PMID 33731208, 2021). "Taken together, current results strongly suggest that transgelin-2 is an interesting and promising target molecule by which immunity can be upregulated in response to infectious and neoplastic diseases." (PMID 33898417, 2021). "Oncogenic roles of transgelin-2 in HCC have been demonstrated, and its high expression is associated with ANXA2, which, in turn, promotes tumor metastasis through the NFκB pathway." (PMID 34575275, 2021). "This upregulation suggests that the activity of transgelin-2 in immune cells is essential during host defense against infectious agents or neoplastic disease." (PMID 33898417, 2021). "Results demonstrated the essential function of Tagln2 in GC tumor angiogenesis, and the proangiogenic activity and mechanism involved in the process were necessary to be studied." (PMID 34150622, 2021). "This action of transgelin-2 is similar to the epithelial protein lost in neoplasm (EPLIN), which inhibits F-actin depolymerization and cross-links filaments in bundles." (PMID 33898417, 2021). "Here, GC tissue microarrays containing 75 tumor tissues and paired normal counterparts were used to assess the expression of Tagln2 in ECs, in which CD34 was used to specifically label ECs." (PMID 34150622, 2021). "Transgelin-2 upregulation in tumor tissue is correlated with clinical stage, tumor size, and neural invasion." (PMID 33898417, 2021).
tumor (continued). "Overall, transgelin-2 is an essential part of the molecular armament required for host defense against neoplasms and infectious diseases." (PMID 33898417, 2021). "Further, we observed a significant reduction in CD8+ tumor-infiltrating lymphocytes (TILs) in the B16F10 tumors from Tagln2−/− DC-injected mice (WT vs. KO, 9.8 ± 1.5 vs. 1.8 ± 1.1)." (PMID 33731208, 2021). "High Tagln2 expression (score >2) was more frequently observed in ECs from tumor tissues (68%) than in ECs from normal tissues (6%)." (PMID 34150622, 2021). "Our findings demonstrated that miR-613 can suppress the progression of PTC cells by targeting TAGLN2, indicating that miR-613 plays the role of a tumor suppressor in PTC." (PMID 34530821, 2021). "Immunohistochemistry performed on an independent tissue chip (n=75) revealed significant upregulation of Tagln2 in tumor-derived ECs which were specifically immunolabeled with CD34." (PMID 34150622, 2021). "Increased expression of TAGLN2 was correlated with deteriorative tumor grade, and the function and regulation made it as a candidate prognostic biomarker." (PMID 33123464, 2020). "Comparatively, TAGLN2 is known as a tumor suppressor whose protective effects are inhibited when phosphorylated by a cdc2-related serine/threonine protein kinase." (PMID 32559205, 2020). "Most of these miRNAs are described as tumor suppressors and have the ability to inhibit cell proliferation by inhibiting transgelin-2." (PMID 30041673, 2018). "Multivariate Cox regression analysis showed that S145 phosphorylation of transgelin-2 (HR = 1.918, p = 0.008) and tumor stage (HR = 2.585, p = 0.004) were independent survival predictors." (PMID 30041673, 2018). "Other studies have demonstrated that TAGLN2 and its homologues have the ability to localize to the nucleus and regulate expression of invasion-related genes that facilitate detachment from tumor cells as well as adhesion to and degradation of the ECM." (PMID 30647847, 2018). "In contrast, cyclin-dependent kinase inhibitors, including p21 and p27 which were identified as tumor suppressors, were increased in the si-TAGLN2 group." (PMID 29110682, 2017). "The overexpression of TAGLN2 in various malignant tumors and its enhancement of tumor migration and invasion have been reported." (PMID 28910360, 2017). "Both oncogenic and tumor suppressive effects of transgelin-2 have been observed depending on the types of tissues investigated." (PMID 28521289, 2017). "This cluster functions as a tumor suppressor targeting the same oncogenic genes such as TAGLN2 and PNP." (PMID 24520312, 2014). "Our previous study demonstrated that tumor suppressive miRNAs, such as miR-1, miR-133a, and miR-145 functioned through repression of LIM and SH3 protein 1 (LASP1), transgelin-2 (TAGLN2), and Switch associated protein 70 (SWAP70)." (PMID 22179486, 2012). "Based on this point, we have sequentially identified tumor suppressive miRNAs and miRNA-mediated molecular targets contributing to cancer cell invasion and metastasis, such as miR-1 regulates TAGLN2, miR-145-FSCN1/LASP1, miR-133a-MSN and miR-138-VIM." (PMID 23159910, 2012). "Meanwhile, studies have reported the down-regulation of transgelin 2 in highly-malignant tumor cells, and our study further expands the significance of transgelin 2 down-regulation to the scope of tumor angiogenesis." (PMID 23056327, 2012). "The authors demonstrated that miR-1 directly targets TAGLN2 and acts as a tumor suppressive microRNA." (PMID 22059741, 2011). "Remarkably, the tumor suppressors miR-1 and miR-133a were both significantly under-expressed in our study, resulting in the activation of the predicted target gene transgelin 2 (TAGLN2), which has been identified as a potential oncogene." (PMID 22140553, 2011). "The immunohistochemistry showed a positive correlation between TAGLN2 expression and tumour grade in clinical BC specimens." (PMID 21304530, 2011).
tumor (continued). "This is the first report demonstrating that tumor suppressive miR-1 directly regulates TAGLN2 in HNSCC cells." (PMID 21378409, 2011). "As a key tumor suppressor at the 5q31 fragile site, miR-145 plays a central role in urological tumors through epigenetic dysregulation (e.g., methylation) and target gene regulation (Transgelin-2, RAB5C, IGF1, etc.)." (PMID 40689207, 2025). "This suggests that while TAGLN2 may contribute to tumor aggressiveness through invasion and metastasis, its direct prognostic value for overall survival in this dataset was not evident." (PMID 41169389, 2025). "We found that TAGLN2 was overexpressed in tumor urine samples as compared with control." (PMID 38473339, 2024). "We hypothesized that tumor-induced suppression of TAGLN2 limits the therapeutic efficacy of CAR T cells in hosts with metastatic OvCa." (PMID 38168227, 2023). "Therefore, it was essential to explore the roles that TAGLN2 affected TME play in tumor development." (PMID 37476180, 2023). "Since dysregulated ER stress responses promote T cell malfunction and immune escape in diverse tumor types, including OvCa17,18,39, we evaluated whether ER stress-inducing conditions altered Tagln2 expression in activated CD8+ T cells." (PMID 38168227, 2023). "We next evaluated whether IRE1α-XBP1s signaling regulates Tagln2 expression in OvCa-infiltrating CD8+ T cells experiencing pathological ER stress in the tumor microenvironment." (PMID 38168227, 2023). "Together, these results indicated that TAGLN2 might serve as an oncogene for tumor development and progression." (PMID 37476180, 2023). "Additionally, IGFBP5, RBMX and TAGLN2, had consistently investigations in peers’ mechanical studies that the three genes were upregulated and promoted tumor metastasis." (PMID 34446747, 2021). "Moreover, reduction of tumor growth control by Tagln2−/− cDC1s strongly suggests that transgelin-2 is an important actin regulator for optimal action of various DC subsets." (PMID 33731208, 2021). "Interestingly, recombinant transgelin-2 protein, engineered for cell-penetration and de-ubiquitination, significantly improved the therapeutic activity of WT BMDCs in controlling tumor growth and metastasis in mice." (PMID 33731208, 2021). "In contrast to inflammatory conditions, because the tumor microenvironment provides an immunosuppressive condition, the expression of transgelin-2 in DCs in a tumor area or tumor draining lymph nodes may be reduced." (PMID 33898417, 2021). "Conversely, these molecular characteristics of transgelin-2 in cancer cells may aid tumor metastasis or tissue invasion." (PMID 33898417, 2021). "In addition, the tumor-infiltrating CD8+ T cells from Tagln2−/− DC-injected mice expressed a lower level of IFNγ than that in WT DC-injected mice." (PMID 33731208, 2021). "Moreover, TAGLN2 is the target of certain tumor-suppressive miRNAs, such as miR-1, miR-133a, miR-145-5p and miR-133b." (PMID 34150622, 2021). "In hepatocellular carcinoma cells with PFTK1 suppression, unphosphorylated Tagln2 inhibits cell motility through its strong actin-binding ability, which possibly abolishes actin cytoskeleton dynamics, thereby suggesting a role as a tumor suppressor." (PMID 34150622, 2021). "However, transgelin-2 acts as a double-edged sword, as its expression is also essential for a wide range of tumor development, including drug resistance and metastasis." (PMID 33898417, 2021). "Recombinant transgelin-2 protein, engineered for cell-penetration and de-ubiquitination, potentiated DC functions to suppress tumor growth and metastasis, demonstrating that this small-actin binding protein represents a promising therapeutic approach for DC-based cancer immunotherapy." (PMID 33731208, 2021). "Recent studies have focused on investigating microRNAs targeting TAGLN2 for tumor suppression." (PMID 32457792, 2020).
tumor (continued). "However, it is known that miR-145-5p can participate in cancer biology through the interactions with multiple downstream oncogenic or tumor suppressive signaling pathways, such as transforming growth factor-β signaling, β-catenin signaling, and TAGLN2." (PMID 30833361, 2019). "ARHGDIA and TAGLN2 have both previously been shown to repress AR transcriptional activity, and to have tumour-suppressive roles; their downregulation has clear implications for PC development, and further supports oncogenic activity of miR-346, 361-3p and -197." (PMID 31043708, 2019). "Tumor size remained significantly correlated with S145 phosphorylation of transgelin-2." (PMID 30041673, 2018). "Thus, TAGLN2 was positively correlated with increasing tumor grade both in the publicly available databases and in our cohort of primary tumor specimens." (PMID 29110682, 2017). "TAGLN2 is upregulated in colorectal cancer and lung adenocarcinoma patient tissue samples and may be involved in tumor development." (PMID 28910360, 2017). "By contrast, transgelin-2 is upregulated in certain tumors and may be involved in tumor development." (PMID 27232882, 2016). "The cross-system effects of transgelin 2 regulation are also an interesting issue, and comparative analysis between tumor cells versus endothelial cells may provide insights involving the transgelin 2 function in tumor pathogenesis." (PMID 23056327, 2012). "In summary, miR-1/miR-133a clusters may function as tumour suppressors through repression of oncogenic TAGLN2 in BC." (PMID 21304530, 2011). "Our data indicate that TAGLN2 may have an oncogenic function and may be regulated by miR-1, a tumor suppressive miRNA in HNSCC." (PMID 21378409, 2011). "Conversely, TAGLN2 mRNA was significantly up-regulated in tumor tissues (P = 0.0209)." (PMID 21378409, 2011). "And the SEREX-defined CT antigen CAGE in HCC may be a potential candidate for tumour vaccine design and transgelin 2 might be an HCC tumour marker for diagnosis." (PMID 15756260, 2005). "Notably, CER T cells recovered from the peritoneal cavity of tumor-bearing mice demonstrated upregulation of Xbp1s and the canonical XBP1s-target genes Sec61a1a and ERdj4, which was accompanied by marked Tagln2 repression, compared with their counterparts prior to infusion." (PMID 38168227, 2023). "Moreover, an analysis was conducted to explore the relationships between TAGLN2 and methylation, copy number values (CNVs), tumor microenvironment (TME), immune cell infiltration, immune-relevance genes, tumor mutation burden (TMB), microsatellite instability (MSI), and IC50." (PMID 37476180, 2023). "In this study, we showed that transgelin-2 is a critical actin-binding protein that supports the migration of DCs to the draining LNs and DC-dependent priming of T cells for clonal proliferation, which are important functions for the host defense against foreign invaders and neoplastic diseases." (PMID 33731208, 2021). "However, it also suggests that this small actin-binding protein may be a molecular target for cancer treatment by boosting the immune response via overexpression of transgelin-2 and suppressing tumor growth or metastasis through its inhibition." (PMID 33898417, 2021). "We speculated that the miR-613/TAGLN2 axis acts as a tumor suppressor in PTC." (PMID 34530821, 2021). "Among three transgelin family members, transgelin-2 is the only isoform that contains an NF-κB consensus motif in the 5′ promoter region and is expressed in immune cells, suggesting that this small protein plays a central role in host defenses against infections and neoplastic diseases." (PMID 33731208, 2021). "Hence, these genes might serve as molecular targets to restrict oncogenic (i.e. ATIC, BZW2) and lipogenic (i.e. CD36, PPARγ), but promote tumor suppressive (i.e. TAGLN2) activity to treat human HCC." (PMID 32559205, 2020).
tumor (continued). "However, these miRNAs can act as tumor suppressors in various human cancers; for instance, miR-1 and miR-133a were found to be frequently down-regulated in bladder cancers, and suppress tumor growth by targeting TAGLN2." (PMID 24855559, 2014). "Our initial analysis focused on characterizing the expression patterns of CXCR7 and TAGLN2 in PTC tissues, revealing significant upregulation of both proteins compared to adjacent non-tumor thyroid tissues (CXCR7, p < 0.001; TAGLN2, p < 0.001)." (PMID 41169389, 2025). "However, HSP90AA1 exhibited an up–down expression pattern along the trajectory, while TAGLN2 remained stable during early differentiation and markedly increased at the later stages, indicating potential roles in fibroblast maturation and tumor microenvironment remodeling." (PMID 40299459, 2025). "Transgelin-2 (TAGLN2), a member of the transgelin family of actin-binding proteins, has been found to play an important role in tumor progression and malignant transformation." (PMID 40867281, 2025). "TAGLN2 had a higher area under the curve (0.901) than CA19-9, a validated tumor biomarker (0.799; P < 0.001)." (PMID 38509504, 2024). "The top GRNs in primary tumors were TCF4, TAGLN2, FOXK1, and BHLHE41, whereas the top upregulated GRNs in recurrent tumor cells were FOXP2, FOXD1, SIX4, and HMGB1." (PMID 39711559, 2024). "Targets also included genes that influence tumor diffusion via metastasis, such as TAGLN2 involved in Transgelin 2 protein expression." (PMID 39336170, 2024). "The mean intensity of TAGLN2 and YBX1 in DAPI+ cells was significantly higher in tumor tissues than in paracancerous tissues." (PMID 39168971, 2024). "Suppression of TAGLN2 in BTC cell lines decreased cell proliferation, migration, invasion, and tumor size, in addition to a reduction in CSC features, including clonogenicity, radioresistance, and chemoresistance." (PMID 38509504, 2024). "Functional studies involving TAGLN2 knockdown and CRNN overexpression demonstrated their inhibitory effects on ESCC cell proliferation, colony formation, organoid growth, and ESCC PDX tumor growth." (PMID 37553345, 2023). "Next, we evaluated TAGLN2 protein expressions based on the HPA database, which displayed the IHC staining results of TAGLN2 protein in tumor and normal tissues." (PMID 37476180, 2023). "For example, TAGLN2, CCND2, and CCL8 were identified in the study and were previously well-established as tumor suppressor genes." (PMID 38234400, 2023). "And in accordance with our findings, we discovered that TAGLN2 was indeed upregulated both in UCEC cell lines and tumor tissues." (PMID 37476180, 2023). "GC tissue microarrays containing 75 tumor tissues and paired normal counterparts from patients with available clinical data was used for IHC analysis of CD34 and Tagln2." (PMID 34150622, 2021). "Transgelin 2 (TAGLN2), an actin-binding protein, is overexpressed in various tumors and thought to be a tumor suppressor." (PMID 32457792, 2020). "Silencing these targets, including tumour suppressors ARHGDIA and TAGLN2, phenocopied miR effects, demonstrating physiological relevance." (PMID 31043708, 2019). "C, TCGA prostate co-expression matrix for CNN2/TAGLN2 PGG family genes and pseudogenes across tumor samples." (PMID 31029062, 2019). "Gene silencing of TAGLN2 in U87MG and U251 significantly inhibited invasion and tumor growth in vitro and in vivo." (PMID 29110682, 2017). "Furthermore, we show that CXCR7 and TAGLN2 physically interact within PTC cells, forming a protein complex that appears to play a critical role in regulating tumor cell invasion and metastasis." (PMID 41169389, 2025). "The expression of YBX1 in DAPI+ cells (r = −0.2739, P = 0.0098) or in TAGLN2+YBX1+ cells (r = −0.2286, P = 0.0322) was negatively correlated with the percentage of CD8+ cells in the tumor region but positively correlated with the percentage of PDL1+ cells (r = 0.2502, P = 0.0187)." (PMID 39168971, 2024).